CLDN8 (claudin 8)
Diseases named in the same sentence as CLDN8 in open-access papers (continued):
Sharing a sentence is not in itself a finding about the gene and the disease.
breast carcinoma (3 papers, 2022 to 2025). "Clinically, low CLDN8 levels have been associated with a higher incidence of lymph node metastasis and poorer outcomes in patients with breast cancer." (PMID 40508219, 2025). "Given that HER2(+) breast cancers often receive agents such as trastuzumab or kinase inhibitors, we analyzed CLDN8’s association with treatment response in HER2+ patient subgroups and validated the findings in HER2-driven cell models." (PMID 40508219, 2025). "We analyzed CLDN8 gene expression in breast cancer patient cohorts to assess its association with clinical outcomes and response to therapy." (PMID 40508219, 2025). "In Grade 3 tumors, CLDN8 expression was significantly reduced, exhibiting a homogeneous staining pattern with minimal membrane localization, further indicating the loss of barrier function in high-grade breast cancer." (PMID 40508219, 2025). "In conclusion, our findings identify CLDN8 as an important prognostic factor in breast cancer and as a novel predictor of treatment response." (PMID 40508219, 2025). "This study systematically explored the role of CLDN8 in breast cancer progression, prognosis, and treatment responses." (PMID 40508219, 2025). "We also established breast cancer cell models with altered CLDN8 expression to examine its effects on cell behavior and drug sensitivity." (PMID 40508219, 2025). "Quantitative analysis of CLDN8 staining intensity across different breast cancer subtypes, grades, and TNM stages further confirmed these findings." (PMID 40508219, 2025). "In this study, we set out to investigate the significance of CLDN8 in breast cancer outcomes and treatment response." (PMID 40508219, 2025). "Data from the Cardiff cohort were used to investigate the prognostic significance of CLDN8 expression in breast cancer." (PMID 40508219, 2025). "The knockdown efficiency of CLDN8 across breast cancer cell lines was confirmed by qPCR and Western blot." (PMID 40508219, 2025). "In ER(+) breast cancer, CLDN8 was primarily membrane-localized with moderate cytoplasmic staining, indicating retained tight junction function." (PMID 40508219, 2025). "We further performed in vitro experiments using breast cancer cell lines with modulated CLDN8 expression (knockdown and control) to assess the influence of CLDN8 on cellular behavior and drug sensitivity." (PMID 40508219, 2025). "CLDN8 expression was also assessed in different molecular subtypes of breast cancer, including ER(+), HER2(+), ER(+)/HER2(+), and triple-negative breast cancer (TNBC) subtypes." (PMID 40508219, 2025). "In one study, CLDN8 was enriched in luminal breast cancers (ER+/PR+), correlating with low grade, low Ki-67, and better prognosis." (PMID 40508219, 2025). "Our work thereby seeks to clarify the clinical value of CLDN8 in breast cancer and lay a foundation for more personalized therapeutic interventions." (PMID 40508219, 2025). "Complementing the clinical observations, we first verified the knockdown efficiency of CLDN8 in various breast cancer cell lines (MCF-7, SKBR-3, MDA-MB-361, and MDA-MB-231)." (PMID 40508219, 2025). "IHC analysis revealed distinct alterations in CLDN8 expression across different histological grades of breast cancer." (PMID 40508219, 2025). "Claudin-8 (CLDN8), a tight junction protein, has emerged as a potential indicator of therapeutic response and prognosis in breast cancer patients." (PMID 40508219, 2025). "This study highlights the complex and context-dependent roles of CLDN8 in breast cancer progression and treatment response." (PMID 40508219, 2025). "Investigating potential combination therapies targeting CLDN8 alongside conventional treatments could provide novel strategies for overcoming drug resistance in patients with breast cancer." (PMID 40508219, 2025). "We then performed in vitro chemosensitivity assays to validate the clinical patterns and directly test whether CLDN8 influences chemotherapy response in breast cancer cells." (PMID 40508219, 2025).
breast carcinoma (continued). "Collectively, these findings underscore the potential of CLDN8 as a marker of favorable prognosis in ER(−) breast cancer, while also highlighting the complexity of its role across various breast cancer subtypes, thus necessitating additional research to elucidate its clinical utility." (PMID 40508219, 2025). "Among the Claudin family, CLDN8 remains relatively unexplored in breast cancer." (PMID 40508219, 2025). "Finally, we investigated the relationship between CLDN8 and the efficacy of standard chemotherapy across breast cancer subtypes." (PMID 40508219, 2025). "Through this comprehensive approach, we address whether CLDN8 can serve as a predictive biomarker for therapy outcomes and explore the potential of targeting CLDN8 in future breast cancer treatment strategies." (PMID 40508219, 2025). "To test this hypothesis, we analyzed clinical breast cancer specimens to correlate CLDN8 expression with disease-free survival and treatment efficacy across various patient subgroups." (PMID 40508219, 2025). "Fucoidan intake has been found to restore the microbiota and intestinal barrier function by regulating tight junction-associated proteins (ZO-1, occludin, claudin-1, and claudin-8) and the MAPK signaling pathway in a 7,12-dimethylbenz[a]anthracene (DMBA)-induced breast cancer rat model." (PMID 35719088, 2022). "Therefore, CLDN8 appears to preserve an endocrine-responsive phenotype, and its high expression correlates with—and functionally contributes to—greater sensitivity to hormonal therapy in breast cancer." (PMID 40508219, 2025). "Therefore, patients with lower CLDN8 expression may be more responsive to these treatments, indicating the potential of CLDN8 as a differential biomarker for tailoring breast cancer therapy." (PMID 40508219, 2025). "To further delineate the impact of CLDN8 on drug sensitivity, we compared the IC50 values between CLDN8 wild-type (WT) and CLDN8 knockdown (KD) breast cancer cell lines for a panel of therapies." (PMID 40508219, 2025). "Notably, AR-driven CLDN8 can activate pro-growth MAPK/AKT signaling in certain contexts, but in ER(+) breast cancer, this may paradoxically reinforce luminal characteristics that endocrine therapy can target effectively." (PMID 40508219, 2025). "Furthermore, our analysis did not reveal a significant association between CLDN8 levels and overall survival (OS) in the studied cohort (p = 0.274), nor did it substantiate the role of CLDN8 as a determinant of DFS in either ER(+) (p = 0.432) or HER2(+) (p = 0.349) breast cancer patients." (PMID 40508219, 2025).
lymphocytic colitis (3 papers, 2020 to 2025). Microscopic colitis characterized by the accumulation of lymphocytes in the colonic epithelium and lamina propria. "It has been shown that pro-inflammatory cytokines, such as TNF-α and IL-15, alter CLDN8 expression and distribution, resulting in lymphocytic colitis, which is characterized by epithelial barrier impairment, leak-flux diarrhea, and abnormal fluid absorption." (PMID 41321497, 2025). "In addition, the expression of proteins Cldn4 and Cldn8 has been shown to decrease in lymphocytic colitis." (PMID 38255781, 2024).
oncocytoma (2 papers, 2010 to 2014). "The distal nephron proteins claudin-7 and claudin-8 have potential use as immunohistochemical biomarkers in the differential diagnosis of chromophobe renal cell carcinoma and oncocytoma." (PMID 20205900, 2010). "Claudin 8, paired box 8,20,21 and KIT overexpression in the oncocytoma-like regions further corroborated the tumor as being from a renal oncocytoma-like lineage." (PMID 25275525, 2014).
osteosarcoma (2 papers, 2017 to 2024). A usually aggressive malignant bone-forming mesenchymal neoplasm, predominantly affecting adolescents and young adults. "Claudin-8 (CLDN8) has been implicated in many cancers, including laryngeal, prostate, and osteosarcoma." (PMID 38540693, 2024).
prostate carcinoma (2 papers, 2019 to 2023). A carcinoma that arises from epithelial cells of the prostate gland. "Moreover, their findings demonstrate that claudin-8 not only regulates intracellular signal transduction and stabilizes the cytoskeleton but also operates as an androgen receptor downstream signal, collectively contributing to the advancement of prostate cancer." (PMID 38188015, 2023).
ulcerative colitis (2 papers, 2023 to 2024). An inflammatory bowel disease involving the mucosal surface of the large intestine and rectum. "We also assessed the expression of claudins Cldn4 and Cldn8 in the colonic mucosa since the expression of Cldn4 has previously been shown to be downregulated in patients with ulcerative colitis." (PMID 38255781, 2024).
ulcers (2 papers, 2021 to 2024). "In particular, claudin-8 was found to be localized in the cell cytoplasm of intestinal epithelia near mucosal erosions and ulcers." (PMID 38334616, 2024). "Furthermore, intestinal surface epithelium in a vicinity of mucosal erosions and ulcers, in addition to decreased membranous claudin-3 expression, showed internalization of claudin-3 and claudin-8 into the cell cytoplasm." (PMID 34867313, 2021).
Anxiety (1 paper, 2023). Intense feelings of nervousness, tension, or panic often arise in response to interpersonal stresses. "We found that IL‐1β, IL‐6, and zo‐1 mRNA levels in the hippocampus positively correlated with anxiety‐like behavior, while ocln and cldn‐8 mRNA levels negatively correlated with anxiety‐like behavior." (PMID 36650644, 2023).
Arthritis (1 paper, 2021). Inflammation of a joint. "Our results show for the first time that a genetic predisposition to gut permeability is pathogenic in a mouse model of arthritis, as claudin-8−/− mice develop a more severe arthritis than WT controls." (PMID 34296202, 2021). "Serum, intestines, and lymphoid organs isolated from K/BxN mice with spontaneous arthritis or from wild-type, genetically modified interleukin (IL)-10R−/−or claudin-8−/−mice with induced arthritis were analyzed by immunofluorescence/histology, ELISA, and flow cytometry." (PMID 34296202, 2021).
asthma (1 paper, 2024). "TJP3 and CLDN8, which contribute to formation of tight junctions and their permeability, had decreased expression which supported the development of the asthma-like phenotype." (PMID 38706568, 2024).
breast tumors (1 paper, 2025). "Notably, CLDN8 expression appears to positively correlate with androgen receptor (AR) status in breast tumors, and patients with concomitantly low CLDN8 and low AR expression have particularly unfavorable prognoses." (PMID 40508219, 2025). "Early evidence indicates that CLDN8 expression is frequently downregulated in breast tumors." (PMID 40508219, 2025).
ductal carcinomas (1 paper, 2018). "Similarly, Claudin 8 (CLDN8), a tight junction protein dysregulated in a number of cancers, is down-regulated in ductal carcinomas compared to the normal breast and is associated with differential survival of patients with ER+/PR+ vs. ER−/PR− disease." (PMID 29301281, 2018).
dysplasia (1 paper, 2009). A usually neoplastic transformation of the cell, associated with altered architectural tissue patterns. "In dysplasia the claudins Cldn2, Cldn4 and Cldn8 were significantly up-regulated, their expression ranged from 4.6–13.31-fold and 4.9–122.38-fold, when transgenic but healthy and non-transgenic lung tissue were compared, respectively." (PMID 19529782, 2009).
Erythema (1 paper, 2025). Redness of the skin, caused by hyperemia of the capillaries in the lower layers of the skin. "We observed a significant reduction in inflammatory erythema, partial restoration of epidermal water loss and stratum corneum hydration, and recovery of CLDN8 expression as evidenced by immunofluorescence analysis." (PMID 40160514, 2025).
joint disease (1 paper, 2021). "Claudin-8−/−mice with constitutively increased gut permeability also develop worse joint disease." (PMID 34296202, 2021).
kidney failure (1 paper, 2025). An acute or chronic condition that is characterized by the inability of the kidneys to adequately filter the blood. "While we have identified promising potential modifier variants in NFU1, DMD, HPS5, CLDN8 and CLDN17, their functional impact on FHHNC progression towards kidney failure remains to be characterized." (PMID 40173198, 2025).
kidney stones (1 paper, 2024). "In this study, CLDN1 expression was found to be increased in patients with a history of recurrent kidney stones and to be highly positively correlated with CLDN4, CLDN7 and CLDN14 and moderately correlated with CLDN2 and CLDN8." (PMID 39345805, 2024).
lymph node metastasis (1 paper, 2025). "A recent study found CLDN8 is upregulated in cervical cancer and associated with lymph node metastasis, marking it as a potential pro-metastatic factor." (PMID 40687428, 2025). "CLDN8 downregulation is associated with lymph node metastasis." (PMID 40687428, 2025). "Low expression of CLDN8 is associated with lymph node metastasis." (PMID 40687428, 2025). "Low CLDN8 expression is associated with lymph node metastasis." (PMID 40687428, 2025). "CLDN8 is upregulated and associated with lymph node metastasis." (PMID 40687428, 2025).
mastitis (1 paper, 2021). Inflammation of breast tissue during lactation or postpartum due to an obstructed duct or infection. "Furthermore, CLDN8 is part of the cell adhesion molecules and leukocyte transendothelial migration pathways, being involved in the recruitment and activation of macrophages during acute Escherichia coli-induced mastitis." (PMID 34440337, 2021). "The claudin 8 (CLDN8) gene on BTA 1 was annotated to the leukocyte transendothelial migration pathway and to the cell adhesion molecules pathway, playing a major role in gene expressions during Escherichia coli-induced mastitis in dairy cows." (PMID 34440337, 2021).
myelomeningocele (1 paper, 2020). Myelomeningocele is the most severe form of spina bifida. "The myelomeningocele patient in our study cohort with the CLDN8 p.P216L variant was of African ancestry." (PMID 32760237, 2020).
oral squamous cell carcinoma (1 paper, 2019). "Similarly, Zhao found that PLAU, CLDN8 and CDKN2A could predict OS using gene expression profiles of GSE13601, GSE30784, GSE37991 and TCGA in oral squamous cell carcinoma." (PMID 30937621, 2019).
prostate tumor (1 paper, 2023). "SPP1 and CLDN8 were upregulated in prostate tumor tissues, whereas COL4A6, RND3, DPT, EFS, and TGFB1I1 were downregulated." (PMID 37251946, 2023).
renal clear cell carcinoma (1 paper, 2022). "In contrast, low levels of CLDN8 expression slow the progression of renal clear cell carcinoma via the EMT/AKT signaling pathway." (PMID 35281827, 2022).
triple-negative breast carcinoma (1 paper, 2025). An invasive breast carcinoma which is negative for expression of estrogen receptor (ER), progesterone receptor (PR), and human epidermal growth factor receptor 2 (HER2). "These patterns persisted upon further stratification, with CLDN8 expression not serving as a significant predictor of DFS in patients with triple-negative breast cancer (p = 0.55), ER(−)/HER2(+) (p = 0.719), or ER(+)/HER2(−) (p = 0.463)." (PMID 40508219, 2025).
tumor (16 papers, 2013 to 2025). "The stark contrast in CLDN8 expression across these subtypes suggests a potential role in tumor biology, particularly in cell adhesion, invasion properties, and response to therapy." (PMID 40508219, 2025). "CLDN8 expression varied significantly across tumor grades, with a marked reduction in Grade 3 compared to Grade 1 (p = 0.022)." (PMID 40508219, 2025). "In summary, CLDN8-high status confers relative resistance to anti-HER2 therapies, whereas CLDN8 depletion or low expression sensitizes tumor cells to HER2-targeted growth inhibition." (PMID 40508219, 2025). "High CLDN8 expression appears to enhance hormone-driven tumor differentiation while buffering cells against cytotoxic stress, explaining its context-dependent effects." (PMID 40508219, 2025). "High CLDN8 levels help tumor cells withstand cytotoxic stress, likely by preserving epithelial integrity and activating survival pathways." (PMID 40508219, 2025). "Immunohistochemistry (IHC) analysis revealed a significant reduction in CLDN8 expression as the tumor grade and TNM stage increased." (PMID 40508219, 2025). "This dualistic behavior of CLDN8 exemplifies how a tight junction protein can function as a double-edged sword in cancer therapy, reinforcing the need to consider the tumor context when predicting treatment response." (PMID 40508219, 2025). "CCL26high OSCC had a characteristic of tumor invasive phenotype with upregulated CLDN8/20 and reduced keratin KRT36, which was significantly associated with EMT markers (CDH1, CDH2, VIM, SNAI2)." (PMID 39931245, 2025). "Subcutaneous tumor models using the CLDN8 knockdown HT29 and SW480 cell lines showed that the tumors were approximately 50% smaller than those grown from the cell lines with normal CLDN8 expression." (PMID 38540693, 2024). "We found that between normal and tumor samples, CLDN8 and CLDN23 were downregulated and CLDN1 and CLDN2 were upregulated, respectively." (PMID 37799140, 2023). "The first gene, CLDN8, is associated with a favorable prognosis in BCa when it is co-expressed with AR, suggesting that CLDN8 acts as a tumor-suppressor gene." (PMID 35568821, 2022). "MMP10, 7, 13 and TIMP1 were reduced in cured mice compared to tumor bearing mice, while Krt5 and Cldn8 levels increased in cured mice." (PMID 34944584, 2021). "For example, Cldn8 expression was predominantly detected in tumor epithelial cells, with very low signal in PBMC." (PMID 28632792, 2017). "Anti-HER2 monoclonal antibodies (e.g., trastuzumab) partly rely on immune-mediated mechanisms and tumor accessibility; CLDN8-high tumors, being more “solid” and less infiltrated, may respond suboptimally." (PMID 40508219, 2025). "As the tumor grade progressed, the CLDN8 expression became more diffuse." (PMID 40508219, 2025). "A starting point may be the HTICS Cell migration pathway genes (Nrp1, Npy, Cldn8) and their substitutes (Klrd1, Spink5, Itga8) identified herein—but other known markers of cancer cell dissemination or circulating tumor cells may be equally informative." (PMID 28632792, 2017). "Using the TIMER database, we detected a negative correlation between the mRNA level expression of CLDN5, CLDN8, CLDN11, and CLDN18 and CRC tumor purity." (PMID 35281827, 2022). "If CLDN8 has a higher expression measurement than MMP3 in a sample, the sample is identified as a normal sample; otherwise, a tumor sample." (PMID 28427173, 2017). "From these gene pairs, we selected a gene pair (CLDN8 and MMP3) with the largest reversal degree between the normal and tumor samples, defined as the signature." (PMID 28427173, 2017). "Transmembrane protein 213 (TMEM213) and Claudin 8 (CLDN8) were detected only in three (0.94 %) and four (1.25 %) tumor specimens, with average folds of 1,066 and 226, respectively." (PMID 24318988, 2014). "CLDN8 is known to participate in tight junction formation and epithelial cohesion; however, its function in tumor biology is not well defined." (PMID 40508219, 2025).
tumor (continued). "The lack of correlation with OS suggests that while CLDN8 may influence early tumor progression, other factors may contribute to long-term survival outcomes." (PMID 40508219, 2025).